IL6 (interleukin 6)
Diseases named in the same sentence as IL6 in open-access papers (continued):
Sharing a sentence is not in itself a finding about the gene and the disease.
vascular dementia (34 papers, 2012 to 2026). A degenerative vascular disorder affecting the brain. "Similar results were found for moderate-to- severe NAFLD, which was associated with increased serum levels of multiple cytokines, i.e., higher IL-6 concentrations partially mediated the association of moderate-to-severe NAFLD with vascular dementia." (PMID 37457589, 2023). "Blood IL6 levels significantly differed between vascular dementia patients and AD patients, and higher IL6 levels were also associated with incident vascular dementia in a meta-analysis of 20 studies." (PMID 37467176, 2023). "Dividing dementia according to aetiology, a moderate to large elevation of both blood IL6 and TNFα levels compared to healthy controls was associated with a vascular dementia diagnosis." (PMID 37467176, 2023). "High IL-6 plasma levels are associated with functional impairment in elderly individuals with vascular dementia." (PMID 32894047, 2020). "Specifically, Gorelick and colleagues suggested that high levels of CRP and IL-6 resulted in nearly a 3-fold increase in vascular dementia risk." (PMID 23308123, 2013). "High levels of plasma IL-6, associated with high CRP, seem to be associated with risk of vascular dementia (VaD), and increased levels of IL-6 and TNF-α are also associated with senescence and frailty in old age." (PMID 23533687, 2013). "IL-6 also affects cognitive function in various diseases, including AD, Lewy body dementia, vascular dementia, cardiovascular disease, etc.." (PMID 36552192, 2022). "Rho-associated protein kinase (ROCK) 1/2, which regulates cellular structure, and inflammatory cytokines (IL-1 and IL-6) were upregulated in the vascular dementia model." (PMID 35203655, 2022). "As was reported, the mRNA expression of TNF-α, IL-6 and IL-1β was decreased in rats of the electroacupuncture group compared with the vascular dementia (VD) group." (PMID 31049031, 2019). "There are also markers of inflammation, such as C-reactive protein levels (CRP) and interleukin-6 (IL-6) that are elevated in the blood plasma of patients with AD and vascular dementia." (PMID 30096929, 2018). "A recent study reported ROCK 1/2, and inflammatory cytokines (IL-1 and IL-6) were upregulated in vascular dementia models while the expression of claudin-5, which maintains the blood–brain barrier, and MAP2 as a nerve cell-specific factor, were decreased in the hippocampal region." (PMID 39779619, 2025). "Finally, in contrast to VVV-BP and ABPV, LF-BPV was negatively associated with the odds of having elevated CRP and with levels of IL-6, consistent with protection against AD and vascular dementia." (PMID 37693005, 2023). "Previous report revealed that patients with vascular dementia had elevated IL-6 values." (PMID 26731740, 2016). "Another RCT of 42 patients with vascular dementia and Fazekas scores of ≥ 2 found a trend towards reduction in WMH volume and inflammatory markers (CRP, IL-6 and tumour necrosis factor-alpha; TNFα) in the RIC group at 6 months follow-up." (PMID 39702489, 2024).
diabetic neuropathy (33 papers, 2011 to 2025). A chronic, pathological complication associated with diabetes mellitus, where nerve damages are incurred due to diabetic microvascular injury involving small blood vessels that supply these nerves, resulting in peripheral and/or autonomic nerve dysfunction. "Elevated levels of IL-6 have been associated with painful diabetic neuropathy compared to painless forms." (PMID 40149566, 2025). "Several epidemiological studies have also demonstrated an association between sub-clinical inflammation (CRP, IL6) and diabetic neuropathy using MNSI." (PMID 35329958, 2022). "Pro-inflammatory cytokines, including TNF-α, IL-1β, and IL-6, are critical drivers in the development of diabetic neuropathy, but chemokines and anti-inflammatory cytokines also play a substantial role in modulating the disease." (PMID 40149566, 2025). "Serum levels of TNF-α, IL-1β, and IL-6 are considerably greater in diabetic neuropathy patients than in healthy people, according to clinical research." (PMID 40149566, 2025). "The ethanolic extract of G. sylvestre reduced the levels of TNF-α, IL-1β, and IL-6 in rats with diabetic neuropathy." (PMID 40006756, 2025). "Inflammatory markers, including TNF-α, IL-6, and high-sensitivity CRP, show elevated levels in diabetic neuropathy but typically achieve lower diagnostic performance (AUC 0.65-0.75) compared to our NSE results (AUC 0.863)." (PMID 40755599, 2025). "Reduced levels of pro-inflammatory cytokines such as TNF-α and IL-6 following gut microbiota intervention have also been shown to correlate with improved symptoms of diabetic neuropathy, including reduced pain and improved peripheral nerve function." (PMID 39727989, 2024). "Apart from the pathophysiological role of cytokines, one study provided diagnostic information using serum levels of IL-6, IL-17, and TNF in patients with diabetic neuropathy." (PMID 36604634, 2023). "IL-6 concentrations were higher in patients with diabetic neuropathy in combination with neuropathic pain, further to those with leprosy neuropathy in combination with neural pain in a comparison with leprosy neuropathy patients without pain." (PMID 32038662, 2020). "Regulatory T cell counts correlated with HbA1c, diabetic neuropathy, lipid spectra parameters, and IL-6 levels." (PMID 28553653, 2017). "The role of inflammation in diabetic neuropathy has also become apparent by the observation of elevated interleukin-6 levels in the presence of this complication." (PMID 21941527, 2011). "In other study, oxidative stress and IL‐6 levels were examined in the diabetic polyneuropathy." (PMID 39474345, 2024). "Additionally, they improve nerve function and alleviate inflammation by suppressing markers like TNF-α and IL-6, underscoring their promise in therapeutic applications for diabetic neuropathy." (PMID 39727989, 2024). "Furthermore, the sildenafil–metformin combination reduced the production of IL-6 and concentration of nitrites, which indicates its ability to reduce inflammation involved in the progression of diabetic neuropathy." (PMID 37629665, 2023). "Furthermore, elevated hs-CRP, IL-6, TNF-α, IL-1 receptor antagonist, and soluble intercellular adhesion molecules have been associated with incident diabetic neuropathy." (PMID 35329958, 2022). "The pro-inflammatory cytokines TNF-α25,43, IL-6 44,45, and NF-κB46 are frontrunner biomarkers for worsening periodontal conditions, and are also potent proinflammatory cytokines involved in the pathogenesis of diabetic neuropathy." (PMID 35788667, 2022). "However, tear level of SP was reported to be decreased in patients with corneal hypesthesia or diabetic neuropathy and to be correlated with a decreased nerve-fiber width in the subbasal nerve plexus and an increased tear concentration of IL-6." (PMID 34575359, 2021). "It is unclear whether IL‐6 is beneficial in developing diabetic neuropathy." (PMID 37795833, 2024).
diabetic neuropathy (continued). "Recent studies have shown that, in STZ-induced diabetic neuropathy, some pronociceptive factors, such as IFN-gamma, IL-1 beta, and IL-6, are upregulated." (PMID 25789329, 2015). "NF-kB inhibition reduces pro-inflammatory mediators such as cyclooxygenase-2 (COX-2), TNF-α, and interleukin-6 (IL-6), while also decreasing oxidative damage markers such as MDA, further highlighting the neuroprotective potential of AMPK enhancers against diabetic neuropathy." (PMID 40806522, 2025). "The pairing of sildenafil and metformin may effectively reduce pain sensitivity in diabetic neuropathy patients by decreasing the activity of iNOS, which is elevated due to elevated levels of inflammatory cytokines like TNF-α and IL-6." (PMID 40149566, 2025). "Another study indicates that inhibition of NF-κB inflammatory cascade using JSH-23 reversed the functional, sensorimotor and biochemical deficits by decreasing neuroinflammation (IL-6, TNF-α, COX-2 and iNOS) and improving antioxidant defence (Nrf2 and HO-1) in diabetic neuropathy." (PMID 34566656, 2021). "While diabetic neuropathies would not be considered as a traumatic pathology per se, a link of dysregulation of IL-6 production in nerve cells as a potential mediator of diabetic neuropathy has been suggested before." (PMID 28512447, 2017). "Several factors may contribute to this decline, including the loss of lower extremity strength and reduced muscle quality by reason of diabetic neuropathy; peripheral arterial disease; increased muscle fat infiltration; and the level of inflammatory cytokines such as THF-a and IL-6." (PMID 25531769, 2014).
edema (33 papers, 2013 to 2026). An abnormal accumulation of fluid beneath the skin, or in one or more cavities of the body. "Experimental data suggest that lowering RR can mitigate VILI, as evidenced by decreased vascular permeability, pulmonary edema, perivascular hemorrhage, and inflammation, including decreased interleukin-6 (IL-6) levels." (PMID 40632387, 2025). "In carrageenan-induced paw edema, increased levels of IL-6 at the site of carrageenan administration facilitate the leukocyte recruitment and mediate edema formation." (PMID 38339059, 2024). "Brain edema is accompanied by IL-1β, IL-6, and TNF-α cytokines, exacerbating mitochondrial dysfunction and increasing ROS levels, leading to neuronal inflammation." (PMID 37529169, 2023). "In vivo, CSE treatment significantly suppressed the expression of pro-inflammatory cytokines TNF-α and IL-6 and relieved the degree of ear edema in the TPA-induced mouse ear edema model." (PMID 37528974, 2023). "The relatively high IL-6 level in the CSF hints that the primary inflammation site is the brain itself, leading to fulminant brain edema." (PMID 37384050, 2023). "After treatment with the miR-124-3p agomir, the degrees of pulmonary injury (e.g. alveolar hemorrhage and interstitial edema), and the increases in IL-1β, IL-6, and TNF-α levels induced by LPS were significantly attenuated." (PMID 32391561, 2020). "IL-6, the main pro-inflammatory cytokine, is pleiotropic and can induce lung edema." (PMID 34421621, 2021). "Here we found that treatment with 2-DG (200 mg/kg i.p. prior to the induction of ventilator-induced ALI) was associated with increased pulmonary edema, attenuated gas exchange, enhanced pulmonary neutrophil accumulation as assessed by MPO levels, and cytokine production (IL-6)." (PMID 24086109, 2013). "We found that AA treatment significantly alleviated radiation-induced lung histopathological damage, reduced inflammatory cytokines IL-1β, IL-4, IL-6, IFN-γ in BALF, mitigated oxidative stress, and improved pulmonary edema and overall health status." (PMID 41564102, 2026). "In these lung protective studies, shionone suppressed the inflammatory response, marker genes, and pathways, such as pulmonary edema, TNF-α, IL-6, and IL-1β and ECM1/STAT5/NF-κB, which again support the anti-inflammatory properties of shionone." (PMID 38202771, 2023). "Studies on the mechanisms suggest that in the early stage of SILI, smoke particles stimulate the body's inflammatory cells to release a large number of inflammatory cytokines such as IL‐1β, IL‐6, TNF‐α, resulting in increased vascular permeability and pulmonary edema." (PMID 39588955, 2024). "In the intracranial hemorrhage (ICH) model, CBL can ameliorate secondary injury and promote behavioral performance during the acute phase by reducing brain edema, the inflammatory response, and BBB permeability by decreasing the expression levels of IL-1β, TNF-a, IL-6, and AQP4." (PMID 36074398, 2022). "Studies have shown that in the process of ALI, activated p38 significantly increases the expression of IL6 and IL1, the following respiratory burst leading to the increase of pulmonary endothelial cell permeability and the formation of pulmonary edema pathologically." (PMID 35799194, 2022). "Our results suggest a reduced expression of pro-inflammatory cytokines including TNF-α, IL-6, IL-1β, and MMP-13 in the ASPP 092 treated ear of the mice in a dose-dependent manner when compared to that of the EPP-induced ear edema mice those are untreated." (PMID 34588910, 2021). "In the study, it was found that after DCXC treatment with 10, 30 and 60 mg/kg, inflammatory cell exudation and pulmonary edema were alleviated to a certain extent, and the levels of TNF-α, IL-6 and IL-1β in BALF were also reduced to a certain extent in a dose-dependent manner." (PMID 31186277, 2019).
edema (continued). "This study showed that high tidal volume ventilation increased total protein, IL-1β, IL-6, RANTES, neutrophil counts, and MPO activity in the BALF and induced lung edema, GEF-H1 and active RhoA expression, Rho-kinase activation, and ultrastructural evidence of endothelial destruction." (PMID 25019086, 2014). "In vivo, pulmonary inflammation, pulmonary edema, ultrastructure changes of type II alveolar epithelial cells, MPO activity, total cells, neutrophils, macrophages, TNF-α, IL-6 and IL-1β in BALF, along with the expression of VCAM-1 and VEGF were dose-dependently attenuated by andrographolide." (PMID 23437127, 2013). "Therefore, PVAC may reduce HCl-induced vascular leakage and neutrophil infiltration by inhibiting IL-6 and TNF-α signaling axis, thereby improving pulmonary edema and lung pathological damage." (PMID 39650159, 2024). "Meanwhile, the increase in TNF-α and IL-6 levels in serum and BALF, as well as the marked increase in W/D weight and total BALF protein content induced by hypoxia were indicative of the occurrence of pulmonary edema and increased pulmonary vascular permeability." (PMID 32112644, 2020).
idiopathic pulmonary fibrosis (33 papers, 2011 to 2026). Idiopathic pulmonary fibrosis (IPF) is a nonneoplastic pulmonary disease that is characterized by the formation of scar tissue within the lungs in the absence of any known cause. "In a study, paracrine signaling from fibroblasts derived from patients with idiopathic pulmonary fibrosis was shown to activate the IL-6/STAT3 and TGF-β/Smad3 pathways in healthy lung fibroblasts, contributing to fibrotic progression." (PMID 40806851, 2025).
leishmaniasis (33 papers, 2009 to 2026). Infectious disease that is transmitted through the bite of hematophagous female phlebotomine sand flies. "Under this study, 3 cytokines (IL-4, IL-6 and IL-10), with a role in increasing susceptibility towards leishmaniasis progression (Th2 response), were estimated in PBMC supernatants." (PMID 38918456, 2024). "Susceptibility to leishmaniasis has been extensively associated with anti-inflammatory cytokines, as demonstrated in IL-4, IL-6, IL-10 and IL-13 deficient BALB/c mice." (PMID 37691941, 2023). "Finally, serum levels of IFN-γ, TNF, CCL2, IL-12p70, IL-6, and IL-10 mediator previously implicated in the progression of leishmaniasis were measured using flow cytometry with the Mouse Inflammation CBA kit." (PMID 41259559, 2025). "However, IL-6 has been strongly associated with leishmaniasis severity and deaths, which may be explained by TNF-α inhibition in early infection." (PMID 32966326, 2020). "IL-6, secreted by several immune cells, presents a controversial role in leishmaniasis acting as anti-inflammatory/pro-inflammatory cytokine." (PMID 40396886, 2025). "In leishmaniasis, IL-6 has been detected in the serum of patients with both visceral and cutaneous forms of the disease and exhibited significant downregulation following treatment." (PMID 38971783, 2024). "Pro-inflammatory cytokines such as IL-1β, IL-6, TNF-α, and IFN-y have been associated with resistance in leishmaniasis." (PMID 38241360, 2024). "LdPP2C affects the host innate immune response by upregulating pro-inflammatory cytokines (TNF-α and IL-6) as well as nitric oxide, while LcPP2C elicits a strong proliferative response of T cells in patients with leishmaniasis." (PMID 33937094, 2021). "Both the IL-10 and IL-6 response is triggered which upregulates in all forms of leishmaniasis and their level subsides as the patients recover from the disease." (PMID 32555598, 2020). "In our studies, nucleotides and AHCC showed the ability to decrease the levels of both IL-6 and IL-9 in infected macrophage/lymphocyte cocultures, which would benefit leishmaniasis patients." (PMID 32867338, 2020). "In this family, IL-6 is confirmed to play a role in leishmaniasis although the nature of this role is controversial." (PMID 33415318, 2020). "Overall, endogenous IL-6 plays a pleiotropic role in leishmaniasis and pinpointing a disease-defining role has proven challenging, perhaps due to the shared gp130 receptor and counter-regulation of inflammatory responses." (PMID 33415318, 2020). "IL-6 is produced by dogs with active leishmaniasis and is a key player in the pathogenesis of canine leishmaniasis." (PMID 31024534, 2019). "The infection causes a strong infiltration of monocytes and leads to the presence of an accumulating number of Mo-Ms which display an M2 phenotype, express IL-6 and harbor parasites which contributes to the fatal outcome of leishmaniasis in these mice." (PMID 29403488, 2018). "The higher production of TNF-α and IL-6 after TLR4a blood stimulation when compared to untreated blood is in agreement with several studies carried out in murine and human leishmaniasis where TLR4 regulated the initial proinflammatory response." (PMID 30539014, 2018). "The expression level of IL-1β by epidermal keratinocytes is one of the decisive factors for generating protective Th1 immunity during experimental Leishmaniasis, along with IL-12, IL-4, IL-6, and osteopontin." (PMID 23286586, 2013). "IL-6 has been reported to play a dual role in leishmaniasis." (PMID 36675185, 2023). "Hence, increased IFN-γ and IL-6 levels as well as decreased amount of IL-10 and IL-4 skewed to the healing process in leishmaniasis." (PMID 30811391, 2019). "Based in these data, we could hypothesize that the antileshmanial effect of CBP involves an immunomodulatory effect in macrophages, increasing NO levels which consequently reduces an exacerbatory cytokine (IL-6) in leishmaniasis." (PMID 28045892, 2017).